ENSG00000260342 (novel protein)
Gene: Protein-coding gene on chromosome 16 (18,788,063 to 18,801,519, reverse strand). Ensembl gene ENSG00000260342.
Genetic constraint (gnomAD): Loss-of-function variants: 8 observed, 22.42 expected, observed/expected ratio (o/e) 0.36, 90% interval 0.21 to 0.64. Missense variants: 159 observed, 262.79 expected, observed/expected ratio (o/e) 0.61, 90% interval 0.53 to 0.69. Synonymous variants: 82 observed, 93.9 expected, observed/expected ratio (o/e) 0.87, 90% interval 0.73 to 1.05.